BTBD19 (BTB domain containing 19)
Tractability: No criterion of Open Targets' tractability assessment is met for any kind of drug.
Gene: Protein-coding gene on chromosome 1 (44,808,523 to 44,817,381, forward strand). Ensembl gene ENSG00000222009.
Subcellular location (Human Protein Atlas): Cytosol
Genetic constraint (gnomAD): Loss-of-function variants: 20 observed, 35.63 expected, observed/expected ratio (o/e) 0.56, 90% interval 0.39 to 0.82. The upper end of that interval is the gene's LOEUF score, 0.82, which puts it in group 3 of 6, group 1 being the genes least tolerant of losing a copy. Missense variants: 325 observed, 397.42 expected, observed/expected ratio (o/e) 0.82, 90% interval 0.75 to 0.9. Synonymous variants: 157 observed, 177.25 expected, observed/expected ratio (o/e) 0.89, 90% interval 0.78 to 1.01.
Homologues: Orthologues: chimpanzee BTBD19 (99% identical), macaque BTBD19 (98% identical), pig BTBD19 (92% identical), guinea pig BTBD19 (89% identical), mouse Btbd19 (89% identical), rabbit BTBD19 (89% identical), dog BTBD19 (88% identical), rat Btbd19 (78% identical), tropical clawed frog btbd19 (49% identical), Drosophila melanogaster axed (22% identical), Caenorhabditis elegans F56C3.9 (13% identical), Caenorhabditis elegans F47B10.9 (10% identical).
Diseases named in the same sentence as BTBD19 in open-access papers:
BTBD19 is named in the same sentence as 4 diseases in open-access papers, as found by Europe PMC text mining. Sharing a sentence is not in itself a finding about the gene and the disease. The quoted sentences say what the papers report.
Fanconi anemia (1 paper, 2015). Fanconi anemia (FA) is a hereditary DNA repair disorder characterized by progressive pancytopenia with bone marrow failure, variable congenital malformations and predisposition to develop hematological or solid tumors. "We performed DRIP-qPCR in four human genes, APOE, RPL13A, EGR1 and BTBD19 in well-established cell lines derived from Fanconi Anemia patients." (PMID 26584049, 2015).
cancer (1 paper, 2025). A tumor composed of atypical neoplastic, often pleomorphic cells that invade other tissues. "This work extends the understanding of BTBD family proteins in cancer, particularly in the context of colorectal carcinogenesis, where BTBD19 emerges as a previously uncharacterized regulator." (PMID 41293263, 2025). "Data from TCGA were harnessed to contrast BTBD19 mRNA expression across pan-cancer and normal tissues, revealing its expression differed in multiple cancer types." (PMID 41293263, 2025). "Given the potential of cancer cells to modulate immune cell polarization via chemokines and their receptors, this study investigated the relationship between BTBD19 expression and chemokine/receptor profiles sourced from the TISIDB database." (PMID 41293263, 2025). "The mRNA and protein expression of BTBD19 was explored in pan-cancer and CRC tissues." (PMID 41293263, 2025).
tumor (1 paper, 2025). "This association highlights a potential mechanistic link between BTBD19 and tumor immune evasion: upregulated PD-L1/PD-1 signaling within the TME dampens cytotoxic T-cell activity, thereby enabling tumors to circumvent immune surveillance." (PMID 41293263, 2025). "KEGG pathways including “Focal adhesion” (implicated in tumor cell motility) and “Relaxin signaling pathway” (linked to angiogenesis and tissue remodeling) were prominently enriched, highlighting BTBD19’s potential impact on CRC progression through microenvironmental modulation." (PMID 41293263, 2025). "BTBD19 expression is associated with enhanced tumor cell invasiveness, which may contribute to CRC progression." (PMID 41293263, 2025). "The enrichment of BTBD19 in M2-associated pathways implies that it may drive macrophage polarization toward an immunosuppressive phenotype, establishing a microenvironment conducive to tumor progression and resistance to immunotherapeutic interventions." (PMID 41293263, 2025). "BTBD19’s dual roles in promoting cell proliferation and shaping a pro-tumor immune landscape highlight its potential as a prognostic biomarker for CRC." (PMID 41293263, 2025). "A pivotal discovery was the robust link between BTBD19 levels and macrophage infiltration, particularly with M2 macrophages-key drivers of tumor-promoting inflammation." (PMID 41293263, 2025). "GO-related gene sets emphasized “Extracellular Matrix Structural Constituent” and “Collagen Containing Extracellular Matrix”, reinforcing BTBD19’s role in ECM-mediated tumor cell interactions." (PMID 41293263, 2025). "These interactions likely drive a feedforward loop where BTBD19 upregulates chemokine signaling, attracting immunosuppressive cells while repelling cytotoxic T cells, thereby fostering a pro-tumor microenvironment." (PMID 41293263, 2025). "These relationships imply that BTBD19 may engage with M2 macrophage-associated pathways to modulate CRC progression and tumor-immune interactions." (PMID 41293263, 2025). "A ROC analysis was carefully performed to fully evaluate BTBD19’s diagnostic potential in CRC, suggesting it may act as a diagnostic biomarker to partly differentiate tumor states from normal conditions." (PMID 41293263, 2025). "Notably, this interplay may underlie the observed poor prognosis in BTBD19-high CRC patients, as PD-L1/PD-1 axis activation is strongly associated with immunosuppressive tumor microenvironments." (PMID 41293263, 2025). "The positive correlation between BTBD19 and these chemokines suggests that BTBD19 may upregulate chemokine expression to recruit M2 macrophages, while M2 TAMs reciprocally secrete additional chemokines and growth factors to sustain BTBD19-mediated tumor progression." (PMID 41293263, 2025). "In summary, BTBD19 emerges as a pivotal node in TME biology, integrating ECM remodeling, immune cell recruitment, and checkpoint signaling to promote a pro-tumor microenvironment." (PMID 41293263, 2025). "Beyond mere descriptive analysis, these results establish a mechanistic framework: BTBD19 likely impacts CRC through modulating ECM dynamics, tumor-microenvironment interactions, and key oncogenic signaling pathways." (PMID 41293263, 2025). "Altogether, these results indicate that BTBD19 may exert influence on immune-cell-related processes in CRC, potentially affecting tumor-immune crosstalk." (PMID 41293263, 2025). "Findings uncovered positive correlations between BTBD19 expression and the ESTIMATE score (R = 0.541, P<0.001), stromal score (R = 0.611, P<0.001), as well as the immune score (R = 0.387, P<0.001), suggesting its linkage to tumor microenvironment components." (PMID 41293263, 2025). "BTBD19 is upregulated in CRC and promotes tumor progression." (PMID 41293263, 2025).
BTBD19 also shares sentences with these, for which no sentence is quoted: colorectal cancer (1 paper).